KLRG1 (killer cell lectin like receptor G1)
Diseases named in the same sentence as KLRG1 in open-access papers (continued):
Sharing a sentence is not in itself a finding about the gene and the disease.
infection (continued). "During the early stage of MCMV infection, KLRG1+ NK cells in the spleen and liver proliferate; the expression of B-cell lymphoma-2 is selectively lost in KLRG1+ NK cells at the late stage of infection, leading to the apoptosis of KLRG1+ NK cells." (PMID 38898461, 2024). "Purified CD127+ and Klrg1+aaMAIT subsets maintained their phenotypes after transfer and infection of recipients." (PMID 37231163, 2023). "To verify how long these changes are maintained, we analyzed NK cells 60 and 90 days post-infection and still observed differential expression of KLRG1 and Eomes." (PMID 37828009, 2023). "Several studies found long lived KLRG1+ CTLs in the vasculature and spleens after infections with different pathogens." (PMID 37426662, 2023). "(E) Quantification of P14 KLRG1+ cells by percent of P14 and total numbers in spleen and liver at days 7 and 31 post infection." (PMID 38127070, 2023). "Klrg1+aaMAIT cells also expressed higher Glut1 receptor compared with their CD127+ counterparts at 40 days post infection." (PMID 37231163, 2023). "Analysis of mice that fate map T-bet expression confirmed that Klrg1+aaMAIT cells were Tbx21-reporter positive, and also expressed T-bet protein at 40 days post infection." (PMID 37231163, 2023). "The lower expression of KLRG1 on T cells found at the disease site is likely related to the poor ability of these cells to migrate to site of infection, as previously demonstrated in murine models." (PMID 36439130, 2022). "Tim3, Lag-3, 4-1BB, and to a lesser extend 2B4 are hallmarks for T cell priming post-primary infection while KLRG1 and Tigit are markers for restimulated and long lived HCMV-specific CD8T responses." (PMID 36532017, 2022). "Because neuraminidase activates TGFβ, small percentages of OTI-Ctrl cells expressed KLRG1 during infection with X31-OVA." (PMID 35942952, 2022). "The lineage-reporting system allows for the identification of a Trm cell-generating population of cells, which initially expresses KLRG1, but loses the expression early post-infection (ex-KLRG1+)." (PMID 34608235, 2022). "In contrast, there was little difference between percentages OTI-TR2Ctrl and OTI-TR2KO that expressed KLRG1 during the early stages of infection with LM-OVA, indicating minimal influence of TGFβ during bacterial infection." (PMID 35942952, 2022). "Intravascular (IV) staining shows that some surviving CTLs maintain KLRG1 expression inside the vasculature during the memory phase of infection." (PMID 35942952, 2022). "In the lungs the progeny of transferred dKO cells are skewed towards a KLRG1+ IL7R− short lived effector (SLEC) phenotype compared to WT cells 10 days after infection." (PMID 35477960, 2022). "Similar populations of KLRG1+ CTLs that were detected after infections with other pathogens are referred to as long-lived effector cells (LLECs), or terminal effector memory CD8 T cells (TTEM)." (PMID 35942952, 2022). "Expression of Klrg1 was similarly localized to cells arising from the MCMV-ie2-gp33 infection, consistent with the known effector-memory phenotype of inflationary CD8+ T cells." (PMID 35185882, 2022). "Large numbers of TEFF cells expressed KLRG1 during infection with LM, while this marker was less prevalent during infection with Vesicular Stomatitis Virus." (PMID 35942952, 2022). "Despite the overall decreased number, the fraction of LCMV-specific CD8+ T cells expressing the effector differentiation marker, KLRG1 was significantly increased at both Days 7 and 10 post infection in DGKζ KO compared to WT mice." (PMID 36846018, 2022). "Compared to WT mice, DGK ζ KO mice exhibited a higher fraction of virus-specific CD8+ T cells, more of which expressed KLRG1 at Day 7 post infection." (PMID 36846018, 2022). "In contrast to WT mice with early infection control, KLRG1+ and/or CD127+ CD8 T cells were drastically reduced in Jinx mice without ATCT." (PMID 36278424, 2022).
infection (continued). "(A) Representative histograms (top) and quantification (bottom) of CD69 MFI on NK cells and frequency of KLRG1+ and IFNγ+ NK cells at day 1.5 post-infection (pi) of 1αKO or FL control mice." (PMID 34396954, 2021). "In contrast, infection with an MPT70-overexpressing Mtb strain promoted highly differentiated KLRG1+CX3CR1+ CD4 T cells with limited lung-homing capacity." (PMID 33879592, 2021). "A TEM cell cluster in the spleen expressing Ly6C, CD27, CXCR3, and CD127 (Sp cluster 12) was more abundant in LCMV Armstrong, whereas a KLRG1+CX3CR1+ subset was more related to MCMV-GP33 infection." (PMID 33458613, 2021). "The largest fraction of cells had a central memory phenotype (CD27+, CD45RO+) that remained stable over time, whereas a shift was found to memory precursor cells based on CD127 and KLRG-1 over time after infection." (PMID 34960178, 2021). "In Mtb-infected mice, CXCR3+KLRG1−Tbetdim T cells migrate into the lung parenchyma and control the infection, while intravascular (iv) T cells have a high expression of KLRG1, CX3CR1, and T-bet." (PMID 33879592, 2021). "The observed maintenance of KLRG‐1+ OT‐I cells in the lung post‐PbA‐OVA infection was interesting, given the traditional view that KLRG‐1+ cells are short‐lived effector T cells." (PMID 34407221, 2021). "This was also evident in a vaccination setting, as MPT70 immunization induced the biggest reduction of CX3CR1+KLRG1+ T cells after H37Rv::mpt70high infection." (PMID 33879592, 2021). "At week 6 post-infection, percentages of KLRG1+ T cells were decreased in vaccinated C57BL/6, IL-23p19−/−, and IL-17A−/− mice to a similar extent." (PMID 34351501, 2021). "While we did not observe major differences between the analyzed mouse groups at week 2 post-infection, vaccination reduced the frequency of KLRG1+ effector T cells in all mice after 3 weeks post-infection." (PMID 34351501, 2021). "We observed that the absence of PTPN2 caused a clear shift in the ratio of CD127−KLRG1+ terminal effector versus CD127+KLRG1− memory precursor CD8 T cells upon infection with Lm-N4." (PMID 32726622, 2020). "In order to further characterize the antigen-specific T cells induced locally in the lung during infection with M. tuberculosis, we measured the expression of the PD-1 and KLRG1." (PMID 33193338, 2020). "Casp-1/11 but not RIP3K deficiency significantly reduced the expression of CD127 with an increase of KLRG1 expression on OT-I CD8+ T cells after 7 days of infection." (PMID 32328060, 2020). "Next, we sorted the top and bottom 25% of GFP expressing T cells from Nur77-GFP mice on day 10 post-infection, which have similar frequencies of effector populations defined by KLRG1 and CD127, and adoptively transferred them into timed-infected recipients." (PMID 31558776, 2020). "Consistent with our previous observations, LEC-educated cells acquired a predominantly effector phenotype (CD44+CD62L−) by d8 post-infection, and most were found within the KLRG1+CD127− subset." (PMID 31988323, 2020). "In sharp contrast, KLRG1 expression was found to be 37.8% ± 3.4% among Ag-specific cells during onset of infection, whereas it decreased to 19.8% ± 2.7% at 30 days." (PMID 31655062, 2019). "At day 6.5 post infection, ST2-deficient P14 cells isolated from spleen and lymph nodes showed a reduced expression of KLRG1." (PMID 31447845, 2019). "As the limit for memory inflation is already determined early during infection, changing the balance between early primed KLRG1- and KLRG1+ cells is of interest for the efficacy of CMV-based vaccine vectors as well." (PMID 31083700, 2019). "Overall, CD8 T cells specific for CMV show low expression of KIRs and NKG2C and increased expression of CD85j, NKG2A and KLRG1 during the latent phase of the infection." (PMID 30989333, 2019). "Transcriptomic analyses also indicated upregulation of Klrg1 in CD8+ T cells from Mtb-infected mice at W12 post-infection." (PMID 31825836, 2019).
infection (continued). "By further characterizing antiviral CD4 T cells in the absence of IL-27R signaling, we demonstrated a dramatic increase in the proportion of cells expressing KLRG1 that was maintained throughout the course of infection." (PMID 30044874, 2018). "Of note, displaying the expression pattern of markers used to identify SLECs (CD127−/KLRG1+) does not absolutely preclude long-term memory formation, as a small percentage of CD127−/KLRG1+ cells can be found months after infection." (PMID 30515169, 2018). "Kinetic studies of brain-infiltrating CD8+ T cells using WT and PD-L1 KO animals revealed that KLRG1+ cells were present within the brain during the acute phase of infection." (PMID 28407741, 2017). "In wild-type (WT) animals, we observed a switch in the phenotype of brain-infiltrating CD8+ T cell populations from KLRG1+ CD127− (SLEC) to KLRG1− CD127+ (MPEC) during transition from acute through chronic phases of infection." (PMID 28407741, 2017). "During the acute phase of infection (i.e., 7 dpi), KLRG1 expression, which decreased by 30 dpi, was observed in both PD-1 KO and WT animals." (PMID 28407741, 2017). "Total numbers of CD8+ T cells did not significantly increase at any point in time but a significant increase of the frequency of CD11a+ and KLRG1+ CD8+ T cells was observed on day 7 after infection." (PMID 28222146, 2017). "We therefore conclude that low titer infections induce partial inflation of virus-specific TEM cells, and that KLRG1 expression of these cells is diminished relative to TEM developing after high titer infections." (PMID 27870919, 2016). "Further evidence for terminal differentiation of NK cells in the absence of perforin was provided by following the expression of KLRG1 at different time points after infection." (PMID 27092144, 2016). "We found that at the chronic infection stage at day 60 post-infection, both Kb-/-Db-/-M3-/- and B6 mice had increased expression of KLRG-1 and PD-1 on CD8+ TEFF cells compared to naïve controls." (PMID 27272249, 2016). "The frequencies of KLRG1+ cNK cells increased in both site of infection and in the periphery in a response to all infections." (PMID 27721814, 2016). "cNK cell maturation as measured by CD27, CD11b, and KLRG1 was affected after infection with different parasite strains." (PMID 27721814, 2016). "Surface marker profiles also differed with time, with expression of CD127, CD62L, CD27, and CD122 increasing and expression of KLRG1 decreasing with time after infection." (PMID 26485703, 2015). "This led us to analyse GFP (CX3CR1) expression in CD62LhiCD127+KLRG1neg TCM, CD62LlowCD127+KLRG1neg TEM and KLRG1+CD8+ T cells derived from naïve OT-ICX3CR1-GFP T cells at 60 days after AdOVA infection." (PMID 26404698, 2015). "E-cadherin (CDH1), the ligand for the inhibitory NK receptor KLRG-1 (killer cell lectin-like receptor subfamily G member 1), was dramatically upregulated during infection." (PMID 24906157, 2014). "It is, therefore, conceivable that other CD8+ T cells with low expression of KLRG1 are generated during this infection/cure regimen." (PMID 24620841, 2014). "Intriguingly, KLRG-1 expression was almost entirely restricted to the effector CD4+ T-bet+ population and very few T-bet−effector CD4+ T cells expressed KLRG-1 in either WT or WSX-1−/− mice on day 14 of infection." (PMID 23593003, 2013). "We then evaluated whether trTregs, identified by co-expression of ST2 and KLRG-1, exhibited the distinctive phenotype of tissue repair cells during infection, distinguishing them from classic ST2- KLRG-1- lymphoid-like Tregs as described in other settings." (PMID 39883714, 2025). "Furthermore, a large proportion of m59- and m139-specific CD8+ T cells displayed effector markers, including high expression of KLRG1 (killer cell lectin-like receptor subfamily G1) at various time points following infection." (PMID 41417899, 2025).
infection (continued). "Similarly in the spleen, we found higher frequencies of CD25+PD‐1+ and PD‐1+ SFV‐specific CD8+ T cells in coinfection, but the proportion of CD38+KLRG1+ was higher in SFV‐only infection at 7 dpi." (PMID 39971320, 2025). "However, there remains a lack of information regarding specific subtypes associated with infection and aging such as T cell immunoglobulin and ITIM domain (TIGIT) and Killer cell lectin-like receptor subfamily G member 1 (KLRG1) as well as T regulatory cells." (PMID 40475763, 2025). "At this stage of infection, about 80% of the KLRG1+ cells were IRF-5+." (PMID 40494997, 2025). "For KLRG1, cell cycle, infection, and immune‐related pathways were enriched in both diseases." (PMID 41291399, 2025). "We found that the frequency of NP+CD8+ T cells in the lung and spleen was similar between Brd7fl/fl mice and Brd7ΔT mice, while a reduction of antigen-specific KLRG1+IL-7R– SLECs was found in the Brd7ΔT mice after infection with HKx31 viruses of previously PR8-primed mice." (PMID 38954484, 2024). "However, stimulation of NK cells with IL-12 + IL-18 induced KLRG1 and resulted in Eomes downregulation, implying that some inflammatory cytokines produced upon infection can reduce Eomes expression and functional capacity of NK cells." (PMID 37828009, 2023). "To determine whether this profound downregulation of Eomes in NK cells during perinatal MCMV infection also occurs upon infection of adult mice, we analyzed NK cell maturation, KLRG1 and Eomes expression at day 21 following the infection of adult C57BL/6 mice." (PMID 37828009, 2023). "Hence, cells with lower expression of KLRG1 play a central role, because their proliferative potential can maintain the T cells in the tissue as the infection lasts." (PMID 37520577, 2023). "Infection with LM elicits a robust inflammatory that favors formation of TEFF that express KLRG1." (PMID 37426662, 2023). "However, we found ST2+(KLRG1+/-) ILC2 accumulation in the lungs peaked at day 9 post-infection, with increased levels of ILC2s in circulation at this time point." (PMID 37251384, 2023). "Together, these data indicate that the therapy-elicited effector T cells, identified by the activation markers CD431B11, NKG2A, and KLRG1, are characterized by dynamic expansion/contraction kinetics resembling those of vaccine- or infection-provoked T cell responses." (PMID 36796366, 2023). "The expansion of Klrg1+aaMAIT cells could be due to increased proliferation as they expressed increased Ki67 after infection." (PMID 37231163, 2023). "The studies presented here show that TCR engagement of activated CD8+ T cells in a secondary site of infection correlated with profound transcriptional changes and expression of markers of effector T cells (for example co-expression of KLRG1 and CX3CR1 and cytokine production)." (PMID 35727849, 2022). "Altogether, these results suggest that targeting KLRG1 on effector cells might be beneficial to accelerate clearance of infection or cancer." (PMID 35572605, 2022). "Genes characteristic of T cell exhaustion were upregulated in the chronic LCMV infection (e.g., Pdcd1, Tox, Lag3), whereas genes associated with memory formation and inflationary phenotypes were upregulated in the acute LCMV (e.g., Il7r) and latent MCMV (e.g., Klrg1) infections." (PMID 35185882, 2022). "Performing differential gene expression analysis between the aged groups emphasized the presence of the inflationary T-cell phenotype (e.g., expression of Klrg1, Gzma, Zeb2) following infection with MCMV-ie2-gp33 compared to mice infected with acute LCMV or MCMV-m45-gp33." (PMID 36028771, 2022). "Thus Tim3, Lag-3, 4-1BB and 2B4 are hallmarks for T cell priming post-primary infection, and restimulaion for 2B4, while KLRG1 and Tigit are markers for restimulated and long lived HCMV-specific CD8T cells responses." (PMID 36532017, 2022). "A role for KLRG1 on CD4+ T cells during infection has also been documented." (PMID 35572605, 2022).
infection (continued). "However, despite the elevated expression of these receptors by Mir142–/– ILC2s from naive mice, ST2 expression was further enhanced by Mir142–/– ILC2s in response to infection as was Klrg1." (PMID 34021046, 2021). "Moreover, one TEM cell cluster (Lu cluster 7) expressing Ly6C and CD127 was uniquely related to LCMV Armstrong, whereas upon MCMV-GP33 infection TEM cells with a KLRG1+CX3CR1+ phenotype were more abundant." (PMID 33458613, 2021). "Memory and functional profiles induced upon early infection were sustained at stable proportions once M.tb infection is established, with the exception of highly differentiated KLRG-1+IFN-γ+TNF+ TE cells, which were more abundant during persistent QFT+ compared to recent QFT conversion." (PMID 33610126, 2021). "TEM cell subsets, however, were mainly responsible for the difference between LCMV Armstrong and MCMV-GP33 infections, with Ly6C+KLRG1−CD127+ cells being more abundant in LCMV Armstrong and KLRG1+CX3CR1+NKG2A+ GP33-specific CD8+ TEM cells defining the phenotype after MCMV-GP33 infection." (PMID 33458613, 2021). "Moreover, the number of early primed KLRG1- CMV-specific T cells in the acute phase of infection set the limit for memory T cell inflation." (PMID 31083700, 2019). "Moreover, when more KLRG1- Maxi cells were transferred, also a higher number of Maxi cells was found in the spleen and the lungs at day 42 post infection." (PMID 31083700, 2019). "In addition to lack of expansion, CD8+ T cells from Ezh2-c-KO mice were all effector cells (CD127−KLRG1+) with little memory precursor cells (CD127+KLRG1−) at day 12 post LM-OVA infection." (PMID 29632530, 2018). "Having confirmed the cell type specific deletion of Il-27p28 in both genetic models, we next, analyzed KLRG1 and GrzA expression at different time points post infection to investigate which cellular source was important for IL-27 mediated regulation of a cytotoxic phenotype in antiviral CD4 T cells." (PMID 30044874, 2018). "In our experimental approach, the combination of the anti-DC-SIGN antibody conjugated to P25 with zymosan resulted in the strongest immune response in terms of cytokine production and also showed increased percentages of total KLRG1+ CD4+ T cells 5 days post-infection." (PMID 29662482, 2018). "Moreover, also in the spleen and the infection site liver, development of Arl4d−/− T cells into KLRG1+CD127− SLEC was more pronounced, similar to the observation in the blood." (PMID 30382149, 2018). "Sorted NK cells expressed higher abundance of Klrg1 upon infection, as well." (PMID 29040326, 2017). "To determine whether this increase in CD8+ T cell numbers could be due to differences in activation and differentiation, we looked at the expression of CD25, CD62L, and KLRG1 on the OVA-specific CD8+ T cells on day 5 after infection." (PMID 29163545, 2017). "In addition, expression of CD127, CD62L, and CD27 progressively increased and expression of KLRG1 progressively decreased with time after infection among CD8lo/CD11ahi cells in individual inbred mice." (PMID 29213267, 2017). "Hence, a lower infection dose resulted in more KLRG-1-expressing Th1 cells, but although this was exacerbated following all antibody treatment, it did not appear to explain why GITR activation reversed the anti-parasitic effects of IL-10 signaling blockade." (PMID 26872334, 2016). "In contrast, after cps1-1 infection, only mature CD11b+ cNK cells expressed KLRG1." (PMID 27721814, 2016). "Infection also increased mature KLRG1+ cNK cell numbers adding support for this hypothesis because mature cNK cells are more capable of migration than proliferation." (PMID 27721814, 2016). "Since we observed the increase in the immature CD11b− cNK cell subsets and, simultaneously, an increase in highly mature KLRG1+ cNK cells after RH and ME49 infections, we, next, assessed the distribution of KLRG1+ cNK cells between CD11b− (R0, R1) and CD11b+ (R2, R3) subsets." (PMID 27721814, 2016).